INS (insulin)
Diseases named in the same sentence as INS in open-access papers (continued):
Sharing a sentence is not in itself a finding about the gene and the disease.
Insulin resistance (continued). "Pearson analyses were performed to assess the relationships between the serum 25(OH)D3 level, serum insulin level, and insulin resistance degree measured by HOMA-IR." (PMID 36362806, 2022). "This MUN phenotype also exhibits impaired insulin secretion capacity and insulin resistance, insufficient cardio-respiratory fitness, and increased carotid intima-media thickness (cIMT)." (PMID 34874895, 2022). "The main physio-pathological process of T2DM is the state of sustained hyperglycaemia attributed to pancreatic β-cells impaired insulin secretion or/and cell insulin resistance." (PMID 35807957, 2022). "DM is characterized by high levels of glycemia and insulinemia due to impaired insulin secretion and insulin sensitivity of the cells, known as insulin resistance." (PMID 35054888, 2022). "In the pre-diabetic state, early insulin resistance leads to a compensatory increase in insulin secretion." (PMID 35898447, 2022). "The control of glucose in pregnancy is complex with a state of insulin resistance combined with stimulation of insulin production by lactogenic hormones." (PMID 34897472, 2022). "The relationship between PCOS and insulin resistance has proven that insulin particularly is a crucial hormone in females of the reproductive age group." (PMID 36407241, 2022). "It is possible that foals adapted to produce insulin to preserve energy during the critical transition into extrauterine life, but also as a protective mechanism against insulin resistance." (PMID 35030228, 2022). "Insulin resistance is defined as a blunting of the PI3K insulin signaling pathway and chronic overactivation of GSK3β is an expected outcome of this state." (PMID 36038539, 2022). "Stress-induced hyperglycemia (SIH) occurs due to an illness that leads to insulin resistance and decreased insulin secretion." (PMID 35959169, 2022). "Risk factors for cardiometabolic diseases (pro- and anti-inflammatory cytokines, plasma insulin, Homeostatic Model Assessment of Insulin Resistance - HOMA-IR, blood pressure) were measured following an overnight fast." (PMID 36589781, 2022). "It is clear that high insulin level is needed to overcome high insulin resistance in the very early gestational period." (PMID 36654578, 2022). "In hyperglycemic patients, insulin is relatively insufficient due to insulin resistance, and glucose utilization is reduced." (PMID 36159470, 2022). "Recently in vivo and in vitro studies have shown methylation of DNA and histone modifications both connect changes in insulin signaling genes and PPARγ itself to insulin resistance." (PMID 34863942, 2022). "Insulin resistance is typically defined as a failure of body and brain cells to respond to insulin and consists of a reduced ability to stimulate glucose utilization." (PMID 35741464, 2022). "Different from type 1 diabetes, the core pathophysiological feature of type 2 diabetes is insulin resistance, accompanied by the decline of insulin’s ability to regulate glucose metabolism." (PMID 36035393, 2022). "Several human clinical trials found a significant positive correlation of serum insulin levels and insulin resistance indices with psoriasis severity." (PMID 36589440, 2022). "Insulin resistance is characterized by a diminished ability of insulin to initiate insulin metabolic signaling and glucose uptake." (PMID 36012219, 2022). "The correct dosage of insulin depends on many factors, such as the time of day and insulin resistance." (PMID 35160077, 2022). "Systemic low-grade inflammation reduces the responsiveness of the peripheral tissues to insulin, leading to insulin resistance." (PMID 36359273, 2022). "Insulin resistance can lead to lipogenesis, as shown by the rapid growth of zebrafish in the first and second insulin inductions." (PMID 35955446, 2022).
Insulin resistance (continued). "The outcomes of this study were in contrast to the findings of another study reporting that insulin resistance, fasting insulin levels and glucose infusion rates were all improved after HIIT interventions in women with PCOS." (PMID 35060480, 2022). "TNFα released into the tissue is recognized by its receptors TNF-R1 to stimulate lipolysis and apoptotic processes and TNF-R2, involved in insulin resistance through inhibition of insulin signaling." (PMID 35276970, 2022). "As there was little fall in blood glucose concentration after insulin injection, these mice developed strong insulin resistance on the Western diet." (PMID 35740449, 2022). "Insulin resistance affects insulin-sensitive tissues (skeletal muscle, liver, and adipose tissue), evoking less responsiveness to insulin action, and resulting in impaired glucose uptake, glycogen synthesis, and glucose utilization for energy production." (PMID 36360310, 2022). "Insulin resistance is defined as reduced responsiveness to high physiological insulin levels in insulin-targeting tissues, and it is considered an important pathogenesis of T2DM." (PMID 36675721, 2022). "There is substantial evidence that insulin resistance, typically defined as a decreased of insulin sensitivity, is a precursor of metabolic syndrome and T2D42." (PMID 35768618, 2022). "With the delivery of the placenta, insulin resistance is significantly reduced, and the insulin concentration is significantly increased." (PMID 35585514, 2022). "This paradoxical outcome is likely a result of an increased insulin secretion and lower insulin resistance in response to treatment." (PMID 36361612, 2022). "It must be emphasized that insulin resistance exhausts beta cells through high insulin demand and compensatory hyperinsulinemia eventually affecting their survival." (PMID 36246880, 2022). "For instance, TNF-α increases insulin resistance by affecting the insulin receptor and subsequent insulin signaling cascades." (PMID 36558427, 2022). "Insulin resistance is a prominent component of cardiovascular disorders due to its involvement in the generation of endothelial dysfunction, since insulin plays a relevant role in vascular homeostasis." (PMID 36145322, 2022). "The insulin-signaling pathway is impaired in MetS due to multiple factors, highlighting abdominal obesity and insulin resistance." (PMID 36233611, 2022). "The HFD control showed increased blood glucose, insulin, and HbA1c levels, indicating insulin resistance and hyperglycemia characterized in T2DM." (PMID 35326230, 2022). "Mice fed with a high fructose diet developed signs of T2D, which include insulin resistance as measured by hyperinsulinemic-euglycemic clamps and elevated fasting insulin level." (PMID 35055468, 2022). "In parallel, insulin resistance with reduced INS production and reduced sensitivity of adipose tissue to INS was confirmed in cows during NEB." (PMID 36355173, 2022). "As increased TNF-α and IL-6 are associated with the pathogenesis of insulin resistance, biologic DMARDs (e.g., TNF inhibitors and tocilizumab) were expected to decrease DM risk by increasing insulin sensitivity." (PMID 35456202, 2022). "The features of OZRs include insulin resistance, hyperinsulinemia, glucose intolerance, dyslipidemia, and compromised insulin signaling in the skeletal muscle and liver." (PMID 36547071, 2022). "UC-MSCs treatment reduced daily insulin requirement, decreased HbA1c levels, and ameliorated insulin resistance in a time-dependent manner." (PMID 35505375, 2022). "In the present study, corroborating these authors, lower serum insulin levels were obtained in RL group, which demonstrates lower insulin resistance in the same group and differs from PS group - which had prolonged fasting." (PMID 35019120, 2022). "Glucotoxicity can eventually lead to insulin resistance, which is the inability of insulin target tissues to respond effectively to insulin." (PMID 36290699, 2022).
Insulin resistance (continued). "C peptide is a well-known biomarker of insulin production because it is likewise secreted by the pancreas' beta cells and is used to diagnose insulin resistance because it has a significantly longer half-life than insulin." (PMID 36128550, 2022). "Knockout experiments confirm that type 2 diabetes is a “2-hit” disease, in which insulin resistance is necessarily accompanied by a ß-defect, preventing the compensatory up-regulation of insulin secretion." (PMID 35646110, 2022). "Another evaluation of insulin resistance is estimated as the insulin area under the curve (AUC) of 7000 μIU/mL or more in 120 min." (PMID 36009471, 2022). "The results were consistent with the previously reported results in other animal models, in which lack of SIRP-alpha protected mice from acute kidney injury and increasing insulin sensitivity in inflammation-mediated insulin resistance." (PMID 35634325, 2022). "Higher levels of insulin and insulin resistance markers were also noted, as well as lower values of the C-peptide index; of these, the significant differences were for HOMA C-peptide (p = 0.028) and C-peptide index (p = 0.032)." (PMID 36143268, 2022). "Plasma insulin was further determined, and a steady increase was shown in WT as the insulin resistance developed under HFD treatment." (PMID 35831364, 2022). "Insulin resistance and diminished insulin secretion are key characteristics of the progression to type 2 diabetes, and are often used as outcomes in intervention trials aimed at preventing the development of type 2 diabetes." (PMID 35631177, 2022). "Reduced insulin resistance leads to improved insulin sensitivity, which increases the activity of eNOS and Akt." (PMID 35622745, 2022). "Skeletal muscle is the major site of insulin-stimulated glucose disposal, and, hence, a predominant site of insulin resistance in T2D." (PMID 35805088, 2022). "Global and skeletal-specific PAK1 knockout mice displayed insulin resistance and reduced insulin-stimulated GLUT4 translocation; this observation is reminiscent of GLUT4 whole-body knockout." (PMID 35774142, 2022). "In obese children, irisin concentrations have been correlated to glucose and insulin levels as well as insulin resistance." (PMID 35774143, 2022). "As such, short-term high-fat feeding in rodents leads to impairment in MBF responses to insulin, and microvascular insulin resistance occurs before metabolic insulin resistance." (PMID 35676248, 2022). "Insulin resistance is primarily compensated by elevated insulin secretion, which eventually leads to T2DM due to the exhaustion of pancreatic β-cells." (PMID 36045953, 2022). "We evaluated the effect of SGLT2i treatment on insulin resistance and whole-body insulin clearance by the glucose clamp method, and we evaluated the effect on hepatic insulin clearance and beta-cell function by a meal tolerance test in Japanese individuals." (PMID 35115614, 2022). "Insulin resistance can be treated by either directly interfering with the insulin signal pathway or by inducing inflammatory responses in individuals with normal levels of metabolic adipokine disease." (PMID 35456284, 2022). "HOMA-IR = homeostasis model assessment–estimated insulin resistance: [Fasting insulin (μU/L) × fasting glucose (nmol/L)]/22.5." (PMID 36364884, 2022). "Such a finding is in line with reports by Cai, Xia who showed that insulin secretion/insulin resistance index was useful as a predictor of development of T2DM." (PMID 35958851, 2022). "We then investigated the insulin/AKT/GSK3β pathway, which is a central insulin signaling pathway that is attenuated in insulin resistance." (PMID 36477360, 2022). "Clinical trials with insulin therapy face challenges because of concerns of off-target effects, limited penetration to the affected areas, and the potential for development of insulin resistance." (PMID 36162508, 2022).
Insulin resistance (continued). "At baseline, those submitted to surgery had slightly lower fasting insulin and insulin resistance compared with controls." (PMID 36551255, 2022). "T2DM usually develops after a long period of increased insulin resistance (IR) where increased insulin concentrations become necessary to activate insulin effects in tissues such as liver and muscle." (PMID 36145186, 2022). "Hypertrophic adipocytes produce abnormal adipokines and cytokines, such as TNF-alpha, MCP-1, FFA, IL-6, and resistin, which inhibit insulin signaling in hepatocytes and induce insulin resistance." (PMID 36615686, 2022). "Insulin resistance (IR) refers to the decline of muscle, fat, or liver sensitivity to insulin due to various reasons, which reduces the efficiency of insulin in promoting glucose uptake and utilization, resulting in insulin resistance or insulin insensitivity." (PMID 36232871, 2022). "For example, if a gene is thought to be involved in insulin resistance, is this gene most proximally modulated by insulin, glucose, or both?" (PMID 35292083, 2022). "Insulin is considered a neurotrophic factor essential for retinal cell survival, and therefore, insulin resistance measured by HOMA-IR contributes to lower average pRNFL thickness." (PMID 35476846, 2022). "Increased GSK3β activity was observed in peripheral insulin-sensitive tissues, including in the skeletal muscle of T2D patients, thus contributing to insulin resistance." (PMID 36499613, 2022). "HOMA-IR, HOMA-β, and QUICKI were used to assess insulin resistance, β-cell function, and insulin sensitivity." (PMID 36297315, 2022). "Insulin resistance in type 2 diabetes has been defined as ‘reduced sensitivity in human body to the action of insulin’, while insulin resistance in the brain can be defined as ‘the failure of neurons to respond to insulin’." (PMID 36819480, 2022). "Six patients showed an improvement in insulin resistance, and further three patients showed a partial improvement in insulin secretion function." (PMID 35409028, 2022). "Since cytokines contribute to insulin resistance, flavone action improves insulin sensitivity in AT." (PMID 36555392, 2022). "Systemic insulin resistance can be a consequence of disturbed insulin signaling in different metabolically active organs such as the liver, skeletal muscles, and adipose tissue." (PMID 36012206, 2022). "The effects of obesity, insulin resistance, and T2D on transendothelial insulin transport are unclear because few studies have addressed this topic in people." (PMID 35054781, 2022). "At the same time, the release of pro-inflammatory cytokines and lipotoxic mediators into bloodstream impairs insulin signaling (insulin resistance, IR) and increases adipocyte lipolysis, followed by alteration of the plasmatic lipid pattern, and lipotoxicity." (PMID 36552572, 2022). "The secondary outcomes included changes from baseline in markers of insulin resistance, insulin sensitivity and beta cell function during an OGTT." (PMID 36267570, 2022). "At present, inositols are considered candidates for classical insulin sensitizers, being useful in the prevention and treatment of GDM; they reduce insulin resistance, the need for insulin in GDM, also improving the lipidic profile." (PMID 35694616, 2022). "Insulin resistance or reduced insulin sensitivity is an important feature of metabolic syndrome, which is associated with obesity, impaired glucose tolerance, inflammation, and hypertension." (PMID 36246058, 2022). "After 24 weeks the supplemented patients showed significant reduction in serum insulin levels, insulin resistance, total cholesterol, LDL-cholesterol, and C-reactive protein with respect to the placebo group." (PMID 35204134, 2022). "When insulin resistance increases, elevated insulin secretion overcomes insulin resistance to normalize the serum glucose concentrations." (PMID 35624721, 2022).
Insulin resistance (continued). "Previous studies have confirmed that serum c-peptide can indirectly reflect the concentration of insulin, and insulin resistance is related to the abnormal increase of insulin content, which is an independent risk factor for the occurrence of CSVD." (PMID 35169393, 2022). "This was preliminarily confirmed by experiments on transgenic mice: those over-expressing GPx1 showed insulin resistance and hyperinsulinemia, while knockout models exhibited improved insulin sensitivity." (PMID 35204134, 2022). "The adipocytes of FABP5-deficient mice exhibited an enhanced capacity for the transport of insulin-dependent glucose and a modest increase in systemic insulin sensitivity while overexpressing FABP5 aggravated insulin resistance and hyperglycaemia." (PMID 35445019, 2022). "Then, via oxidative alteration of important insulin downstream signaling pathways, it inhibits insulin signaling function and contributes to the development of insulin resistance." (PMID 35845577, 2022). "Further buttressing the primary role of hepatic insulin clearance in insulin resistance, global Ceacam1 null mice manifest reduction in insulin clearance at 2 months of age, followed by systemic insulin resistance at 6–7 months of age and hepatic steatosis." (PMID 36009446, 2022). "T2D is now well recognized as a chronic, low-grade inflammatory disease characterized by impaired insulin secretion, insulin resistance, glucose intolerance, and hyperglycemia." (PMID 39872753, 2022). "Wild-type mice fed a HFD developed glucose intolerance and insulin resistance, whereas KA treatment markedly improved glucose tolerance and insulin sensitivity." (PMID 36311752, 2022). "In fact, this insulin resistance and impaired insulin signaling in the brain has been termed type 3 diabetes." (PMID 35887304, 2022). "A treatment using HucMSC-Exos restored islet structure, reduced the homeostatic model assessment of insulin resistance, and enhanced insulin sensitivity by promoting glucose uptake via GLUT1-4 in T2DM rats." (PMID 36339446, 2022). "EC has been shown to alleviate insulin resistance in in vivo animal studies by reducing glucose and insulin levels, refining insulin sensitivity, and improving glucose metabolism." (PMID 35327563, 2022). "In our hands, exposed females but not males also show hallmarks of T2D such as elevated fasting glycemia, glucose intolerance, insulin resistance and reduced plasma insulin." (PMID 36277707, 2022). "Due to the insulin resistance in nonalcoholic fatty liver disease, insulin sensitizers can be used to treat the disease by promoting the binding of insulin to its receptor and accelerating the uptake of glucose into peripheral tissues." (PMID 35469222, 2022). "MOTS-c, fasting blood glucose, insulin, Homeostatic Model Assessment for Insulin Resistance (HOMA-IR), lipid panel, and body mass index levels were assessed." (PMID 35989823, 2022). "Two main types of DM are type 1, insulin-dependent, and type 2, insulin-independent, and insulin resistance plays a crucial role in type 2 DM." (PMID 35610696, 2022). "Since variable degrees of resistance to insulin action were expected in these patients, we also evaluated the main indirect indicators of insulin resistance with the HOMA index, and pancreatic function reserve by assaying serum C-peptide." (PMID 35859794, 2022). "Peripheral and central insulin resistance leads to reduced insulin signalling, increased Aβ toxicity, oxidative stress and even the development of neurodegeneration." (PMID 36003645, 2022). "Various methods have emerged to correct insulin resistance or hyperinsulinism, such as insulin-sensitizing drugs, physical activity, and dietary interventions." (PMID 36368970, 2022). "Being physically active enhances the body’s sensitivity to insulin while countering insulin resistance, with added benefits for people with DM." (PMID 35455929, 2022).